IRF2 (interferon regulatory factor 2)
Description:
DNA-binding transcription factor that specifically binds to the upstream regulatory region of type I interferon (IFN) and IFN-inducible genes and regulates their expression. Mainly acts as a transcription repressor, repressing expression. Also acts as an activator for several genes including H4 and IL7. Constitutively binds to the ISRE promoter to activate IL7. Involved in cell cycle regulation through binding the site II (HiNF-M) promoter region of H4 and activating transcription during cell growth. Antagonizes IRF1 transcriptional activation (By similarity). [Isoform 2]: Unable to bind to IRF2BP1 and IRF2BP2 corepressors and cannot mediate repression.
Synonyms: IRF-2
Tractability: PROTAC: UniProt records ubiquitination sites on it; ubiquitination databases record sites on it.
Gene: Protein-coding gene on chromosome 4 (184,385,702 to 184,474,558, reverse strand). Ensembl gene ENSG00000168310.
Subcellular location: Nucleus; Chromosome
Subcellular location (Human Protein Atlas): Nucleoplasm; Cell Junctions; Cytosol
Pathways (Reactome):
Immune System: Interferon alpha/beta signaling; Interferon gamma signaling
Hemostasis: Factors involved in megakaryocyte development and platelet production
Programmed Cell Death: Pyroptosis
Gene Ontology:
Molecular function: DNA binding; DNA-binding transcription activator activity, RNA polymerase II-specific; DNA-binding transcription factor activity; protein binding; RNA polymerase II transcription regulatory region sequence-specific DNA binding; sequence-specific DNA binding; sequence-specific double-stranded DNA binding; DNA-binding transcription factor activity, RNA polymerase II-specific; DNA-binding transcription repressor activity, RNA polymerase II-specific; RNA polymerase II cis-regulatory region sequence-specific DNA binding; transcription cis-regulatory region binding
Biological process: defense response to virus; positive regulation of transcription by RNA polymerase II; regulation of DNA-templated transcription; regulation of transcription by RNA polymerase II; toll-like receptor 3 signaling pathway; cell population proliferation; immune system process; negative regulation of transcription by RNA polymerase II; negative regulation of type I interferon production
Cellular component: cell junction; chromatin; cytosol; nucleoplasm; chromosome; nucleus
Genetic constraint (gnomAD): Loss-of-function variants: 10 observed, 35.11 expected, observed/expected ratio (o/e) 0.28, 90% interval 0.17 to 0.48. The upper end of that interval is the gene's LOEUF score, 0.48, which puts it in group 2 of 6, group 1 being the genes least tolerant of losing a copy. Missense variants: 268 observed, 413.13 expected, observed/expected ratio (o/e) 0.65, 90% interval 0.59 to 0.72. Synonymous variants: 133 observed, 151.81 expected, observed/expected ratio (o/e) 0.88, 90% interval 0.76 to 1.01.
Homologues: Orthologues: chimpanzee IRF2 (99% identical), macaque IRF2 (99% identical), dog IRF2 (95% identical), pig IRF2 (95% identical), guinea pig IRF2 (93% identical), mouse Irf2 (93% identical), rabbit IRF2 (92% identical), rat Irf2 (92% identical), tropical clawed frog irf2 (69% identical), zebrafish irf2b (47% identical), zebrafish irf2a (46% identical). Paralogues in human: IRF1 (37% identical), IRF5 (23% identical), IRF8 (22% identical), IRF6 (22% identical), IRF4 (21% identical), IRF3 (17% identical), IRF9 (17% identical), IRF7 (16% identical).
Diseases named in the same sentence as IRF2 in open-access papers:
IRF2 is named in the same sentence as 88 diseases in open-access papers, as found by Europe PMC text mining. Sharing a sentence is not in itself a finding about the gene and the disease. The quoted sentences say what the papers report.
colorectal cancer (24 papers, 2016 to 2025). A primary or metastatic malignant neoplasm that affects the colon or rectum. "Lymph node metastasis in patients with colorectal cancer is associated with enriched exosomal IRF-2 (interferon regulatory factor 2) in serum." (PMID 36831450, 2023). "The overexpression of interferon regulatory factor 2 (IRF-2) was observed in the serum exosomes of colorectal cancer patients with lymph node metastasis." (PMID 36901813, 2023). "Another study indicated high IRF2 expression independently predicts poor overall survival in colorectal cancer." (PMID 35012444, 2022). "Higher IRF-2 expression leads to increased responsiveness to anti-PD-1 therapy in colorectal cancer." (PMID 35115027, 2022). "Studies have found that interferon regulatory factor 2 (IRF2) can improve colorectal cancer responsiveness to PD-1 therapy by directly inhibiting chemokine 3 (CXCL3)." (PMID 35923703, 2022). "A recent study found that Kras-IRF2 axis drives immune suppression and immune therapy resistance in colorectal cancer." (PMID 35012444, 2022). "Responsiveness to anti-PD-1 therapy was increased in colorectal cancers with higher IRF2 expression." (PMID 33777798, 2021). "Similarly, CXCL3 is upregulated due to KRAS-mediated inhibition of interferon regulatory factor 2 (IRF2), which exacerbates the recruitment of MDSCs in colorectal cancer." (PMID 40303413, 2025). "However, it has also been demonstrated that IRF2 acts as an oncogene in skin squamous and colorectal cancers." (PMID 34893086, 2021). "Moreover, increased expression of interferon regulatory factor 2 (IRF-2) was detected in plasma EVs of colorectal cancer patients with LNM." (PMID 34552874, 2021). "In colorectal cancer models KRASG12D has shown to downregulate the expression of interferon regulatory factor 2 (IRF2), which in turn suppresses CXCL3 expression, resulting in high expression of CXCL3 and promoting migration of myeloid-derived suppressor cells to the tumor microenvironment." (PMID 33777798, 2021). "As a crucial member of interferon regulatory factor family, the association between the expression of IRF-2 and clinical prognostic significance has not been fully explored in colorectal cancer (CRC)." (PMID 28465494, 2017). "Oncogenic KRAS drives an immune suppressive program in colorectal cancer by repressing interferon regulatory factor 2 expression, and may sensitize lung adenocarcinoma to GSK-J4-induced metabolic and oxidative stress; moreover, KRAS-targeted anticancer strategies have been documented." (PMID 33240468, 2020). "The higher expression of IRF2 were observed in colorectal cancer (CRC) tissues compared to those in paired normal tissues and were significantly associated with distant metastasis and worse OS as well as TNM stage, indicating that IRF2 functioned as an independent prognostic factor in CRC." (PMID 30876449, 2019). "In a mouse colorectal cancer model, KRASG12D expression inhibits T cell infiltration and interferon regulatory factor 2 (IRF2) production and, promotes the migration of CXCR2+ MDSCs into the TME." (PMID 40165901, 2025). "KRAS-mediated repression of interferon regulatory factor 2 (IRF2) results in high expression of CXCL3, which binds to CXCR2 on myeloid-derived suppressor cells (MDSCs) and regulates the immune responses in colorectal cancers." (PMID 40547026, 2025). "In KRAS-mutant colorectal cancer (CRC), KRAS∗-mediated repression of interferon regulatory factor 2 (IRF2) that directly represses CXCL3 expression results in high expression of CXCL3, which binds to CXCR2 on MDSCs and promotes their migration to the TME." (PMID 35003065, 2021).
colorectal cancer (continued). "There are investigations showing that CXCL3 is associated with vascular invasion and tumor capsule formation in HCC and is targeted by IRF2 to suppress MDSC migration and infiltration in colorectal cancer." (PMID 33552958, 2020). "Colorectal cancer-derived exosomes can modify TME in adjacent organs and promote lymphangiogenesis in the sentinel LNs, facilitating distant metastasis via interferon regulatory factor 2 (IRF2) that further induces VEGF-C secretion by TAMs." (PMID 41511312, 2025). "Qi demonstrated that IRF-2 is a transcription factor of CENP-N that promotes CENP-N expression and activates the AKT cascade in nasopharyngeal cancer, while Liao proved that IRF-2 binds to the DNA promoter region of CXCL3 and blocks its transcription in colorectal cancer." (PMID 35115027, 2022). "In addition, it was described that KRASG12D could promote Treg transformation by blocking the interferon regulatory factor 2 (IRF2), resulting in repression of IRF2/CXCL3 pathway and binding of CXCL3 to CXCR2 on MDSCs, driving immune suppression and immune therapy resistance in colorectal cancer." (PMID 35159208, 2022).
hepatocellular carcinoma (12 papers, 2017 to 2024). A malignant tumor that arises from hepatocytes. "Given that IRF2 has the ability to exert antioncogenic activities, IRF2 overexpression led to a dramatic cell death response by apoptosis in hepatocellular carcinoma." (PMID 36199790, 2022). "Collectively, these findings underscore the important role of IRF2 and β-catenin in the signaling pathway of hepatocellular carcinoma." (PMID 33735820, 2021). "IRF2 is down‐regulated in many primary human cancers, including gastric cancer and hepatocellular carcinoma." (PMID 33264494, 2021). "To examine for a relationship between IRF2 and β-catenin, we overexpressed IRF2 or silenced endogenous IRF2 in human hepatoma HepG2 and Huh7 cell lines." (PMID 33735820, 2021). "Since Wnt/β-catenin plays a key role in the signaling pathway of cancer stem cells, IRF2 may influence the stem cell phenotype by regulating β-catenin in hepatocellular carcinoma." (PMID 33735820, 2021). "For instance, IRF1 and IRF2 could de-activate PD-L1 expression in hepatocellular carcinoma." (PMID 38833018, 2024). "Other studies have shown that Sp1, IRF1 and IRF2 can bind to the APOL1 promoter in hepatoma cells, and IRF1, IRF2 and STAT2 to the APOL1 promoter in podocytes and endothelial cells." (PMID 37924378, 2024). "We establish, based on quantitative measurements obtained for the hepatoma cell line Huh7.5, an ordinary differential equation model for IFNα signal transduction that comprises the feedback regulators STAT1, STAT2, IRF9, USP18, SOCS1, SOCS3, and IRF2." (PMID 32696599, 2020).
colon carcinoma (11 papers, 2014 to 2025). "Cellular subtype analysis indicated that IRF2 is primarily expressed in T, NK, B, stroma and myeloid cells in human colon carcinoma." (PMID 38995014, 2024). "We extracted scRNA-seq datasets (GSE178341) and analyzed IRF2 expression profiles in human colon tumors." (PMID 38995014, 2024). "A positive correlation between STAT1, IRF2 and PD-1 is observed in the myeloid cells in human colon cancer patients." (PMID 38995014, 2024). "To illustrate the human cancer relevance of our above findings, we then analyzed the cellular source of IRF2 in colon cancer patients." (PMID 38995014, 2024). "miR-18a inhibits liver metastasis of colon cancer by inducing M1-like polarization due to increased IFN-γ production by targeting interferon regulatory factor 2 (IRF2)." (PMID 29899293, 2018). "PTPN13 promoter activity (encoding Fap1) was repressed by interferon regulatory factor 2 (irf2), and expression of Fap1 and Irf2 were inversely correlated in CD133+ or CD133− colon cancer cells." (PMID 29899829, 2018). "Moreover, Fas-associated phosphatase 1 (Fap1) gene promoter, a ubiquitously expressed tyrosine phosphatase, was repressed by IRF2, impairing the stem cell-like features in a murine xenograft model of colon cancer." (PMID 33735820, 2021). "The rs4648090 polymorphism has also been related to decreased risk of breast cancer among women with European ancestry and to interact with other SNPs in the IFNG, IRF2, IL6, and NFKB1 genes to affect risk of colon cancer, and with IRF6 and NFKB1 genes for risk of rectal cancer." (PMID 30781516, 2019). "We found Irf2 repressed PTPN13 transcription in SW620 colon cancer cells." (PMID 29899829, 2018). "We further determined whether the Irf2 was up-regulated in the metastatic liver tissue of colon cancer patients." (PMID 27028860, 2016). "The molecular mechanisms involved in miR-18a-induced M1 macrophages were further studied and we found that miR-18a-mediated induction of macrophage IFNγ is required for inhibition of liver metastasis of colon cancer and that macrophage IRF2 is targeted by miR-18a." (PMID 27028860, 2016). "Fifteen genes (DUSP2, INFGR1, IL6, IRF2, JAK2, MAP3K10, MMP1, NFkB1A, NOS2A, PIK3CA, SEPX1, SMAD3, TLR2, TYK2, and VDR) were associated with colon cancer mortality (PARTP <0.05); JAK2 (PARTP = 0.0086), PIK3CA (PARTP = 0.0098), and SMAD3 (PARTP = 0.0059) had the strongest associations." (PMID 25541970, 2014). "Fifteen genes (DUSP2, INFGR1, IL6, IRF2, JAK2, MAP3K10, MMP1, NFkB1A, NOS2A, PIK3CA, SEPX1, SMAD3, TLR2, TYK2, and VDR) were significantly associated with colon cancer mortality at the <0.05 level; an additional 15 genes had gene PARTP values between 0.05 and 0.10." (PMID 25541970, 2014). "Within the top 20 TFs that showed high correlation between their own CNV and expression, we observed known colon cancer drivers ZNF703 and SMAD4, as well as IRF2 and GATA6, whose DNA aberrations are likely oncogenic." (PMID 41114645, 2025). "Exosomal transfer of interferon regulatory factor 2 (IRF2) augments VEGFC secretion by sentinel lymph node (SLN) macrophage, leading to lymphangiogenesis and SLN metastasis of colon cancer." (PMID 38741166, 2024). "In colon cancer patients, the expression levels of STAT1, IRF2 and PDCD1 are positively correlated in tumor-infiltrating myeloid cells." (PMID 38995014, 2024). "In human colon cancer patients, the expression levels of STAT1, IRF2 and PDCD1 are positively correlated in tumor-infiltrating myeloid cells." (PMID 38995014, 2024). "Stratified analysis according to disease site revealed IRF-2 expression on overall survival was only pronounced in patients with rectal cancer (P = 0.037), but not with colon cancer (P = 0.084)." (PMID 28465494, 2017).
melanoma (11 papers, 2012 to 2026). A malignant, usually aggressive tumor composed of atypical, neoplastic melanocytes. "Antibodies against either E4F1 or IRF2 consistently resulted in loss of A allele-specific protein binding in both melanoma and breast cancer cell lines." (PMID 41542517, 2026). "Presumably, the loss of IRF2 confers some growth advantage to this melanoma, which is different from what we observed in the mouse melanoma model." (PMID 39281881, 2024). "In any case, the CPI results indicate that similar to mouse B16 cells, loss of IRF2 allows human primary melanomas to evade the host immune response leading to treatment failure." (PMID 39281881, 2024). "Stimulation of the IRF2-deficient melanomas with interferon induced the expression of a functionally homologous transcription factor, IRF1, which then restored the MHC I pathway and responsiveness to CPI." (PMID 39281881, 2024). "In both human and mouse melanomas, loss of IRF2 led to resistance to CPI immunotherapy in preclinical models." (PMID 39281881, 2024). "To test cause and effect for these IRF2 correlations and the consequences of IRF2 loss, we gene-edited IRF2 in a patient-derived melanoma and a mouse melanoma." (PMID 39281881, 2024). "This loss of IRF2 caused both human and mouse melanomas to become resistant to immunotherapy with a checkpoint inhibitor." (PMID 39281881, 2024). "When IRF2 was knocked out of mouse or primary patient melanomas, there was also a reduction in the expression of IRF2 target genes, establishing a cause-and-effect relationship between IRF2 expression and these genes." (PMID 39281881, 2024). "On the other hand, the IRF2-deficient human patient melanoma grew more aggressively in both severely immunodeficient NSG mice and human hematopoietic stem cell transplanted, immunocompetent NSG mice." (PMID 39281881, 2024). "Since type II interferon can also induce IRF1, and this cytokine was FDA-approved for other indications, future studies should examine the effects of type II IFN on melanomas that are IRF2-deficient and its potential as an adjuvant therapy with CPI." (PMID 39281881, 2024). "In particular, we identified proteins that typically act either as a transcriptional repressor (E4F1) or activator (IRF2) as both preferentially binding the A-risk allele of rs3769823, and verified binding of both factors via ChIP in melanoma cells and primary melanocytes." (PMID 41542517, 2026). "We couldn’t detect any proliferation and growth differences in IRF2-deficient mouse melanoma cell line either in vivo or in vitro." (PMID 39281881, 2024). "Role of IRF1 in reversing the immune evasion phenotype in IRF2-deficient B16 melanoma cells." (PMID 39281881, 2024). "To summarize, IRF2 loss doesn’t affect growth of the mice melanoma cells B16F0." (PMID 39281881, 2024). "Moreover, the resistance of IRF2-deficient melanomas to immunotherapy could be restored by treatment with a type I IFN inducer in combination with CPI." (PMID 39281881, 2024). "In contrast, IRF2-deficient primary melanomas were resistant to anti-PD1 therapy and tumor growth and survival were unaffected relative to untreated IRF2-sufficient tumors." (PMID 39281881, 2024). "CRISRPcas9 was used to knock out IRF1 and IRF2 genes in human and mouse melanoma cells and the resulting phenotypes were analyzed in vitro and in vivo." (PMID 39281881, 2024). "Injection of anti-PD1 antibody into mice transplanted with the IRF2-sufficient human primary melanoma significantly (p ≤ 0.5) slowed the growth of this tumor (by 1 week)." (PMID 39281881, 2024). "Similar to primary melanoma cells, loss of IRF2 dropped the surface expression of MHC I and significantly reduced transcripts of TAP2, ERAP1, and PSME1 detected in B16F0 mouse melanoma cells." (PMID 39281881, 2024). "To further evaluate the role of IRF1 in vivo, we examined the therapeutic effect of anti-PD1 + poly(I:C) treatment on IRF1 + IRF2 double knockout melanoma cells." (PMID 39281881, 2024).